MMP2 (matrix metallopeptidase 2)
Diseases named in the same sentence as MMP2 in open-access papers (continued):
Sharing a sentence is not in itself a finding about the gene and the disease.
tumor (continued). "In tumor microenvironment, tumor cells can degrade and remodel the ECM by excessively secreting matrix MMPs such as MMP-2 and MMP-9." (PMID 27042656, 2016). "Our data also indicated that PS341 treatment largely decreased the expression of both MMP2 and MMP9 in HCC and CRC cells, thus restricting the migration capacities of these two tumor types." (PMID 26915315, 2016). "MMP2 and MMP9 have been shown to be crucial for the “angiogenic switch” that occurs upon the initiation of tumor vascularization." (PMID 26979530, 2016). "MMP14 enhances tumor invasion and dissemination through cleavage of CD44, a cell surface glycoprotein, or activation of MMP-2 and MMP9 through a combination of TIMP-2 and MMP14." (PMID 27613828, 2016). "Then, ALK5-ICD translocates to the nucleus and associates with transcriptional co-activator p300, promoting tumor invasion by induction of target genes (SNAIL1, ZEB, and MMP2)." (PMID 27166254, 2016). "The expressions of MMP-2, MMP-7, and MMP-9 were mainly observed in tumor cells and peritumoral stroma." (PMID 27429508, 2016). "MMPs were reported to induce tumor progression in HCC including MMP-1, MMP-2, MMP-3, MMP-7, MMP-9, MMP-11 and MMP-13." (PMID 26882566, 2016). "It has been reported that the PI3K/Akt and p38-MAPK signalings were involved in Aurora-A-induced tumor EMT, invasion as well as MMP-2 activity in a variety of human cancers." (PMID 27793005, 2016). "Staining area and intensity of MMP2 and MMP9 in the MC38 and LLC tumor colonies were notably decreased in the S100A8 and S100A9 knockdown groups compared with controls." (PMID 27086923, 2016). "In contrast, down-regulation of MMP-2 and MMP-9 provides a preventive measure against tumor metastasis." (PMID 27144433, 2016). "Among them, MMP-2 and MMP-9 play key roles in tumor invasion and metastasis because of their specificity for type IV collagen, which is the principal component of the basement membrane." (PMID 26993601, 2016). "During degradation of ECM, MMPs especially MMP-2 and MMP-9 contribute to the proteolysis of the ECM whose degradation products together with tumor cells take part in the VM formation." (PMID 27793002, 2016). "Matrix metalloproteinases (MMPs), including MMP-2 and MMP-9, play essential roles in regulating tumor metastasis and angiogenesis." (PMID 26646323, 2016). "Here we demonstrate that KDM1A advances tumor metastasis by epigenetically silencing the TIMP3 transcription, which in turn stimulates MMP2 expression and JNK phosphorylation." (PMID 27058897, 2016). "Due to their broad distribution in the human body and wide range of hydrolysis substrates, MMP-2 and MMP-9 are regarded as key enzymes for hydrolyzing the ECM and promoting tumor invasion." (PMID 27716341, 2016). "During cancer development, MMP2 and MMP9 degrade the basement membrane as well as promote tumor cell metastasis to distant tissues and/or organs." (PMID 26917087, 2016). "For example, MMP2 and MMP9 were upregulated in pre-cancerous nodules where they promoted a switch to an angiogenic phenotype, resulting in tumor transformation and growth." (PMID 26956475, 2016). "We found that PER1 knockdown not only increased MMP2 and MMP9 expression, but also decreased TIMP-2 expression, presumably leading to the observed increases in tumor cell migration and invasion." (PMID 26943040, 2016). "Of more than 20 known human MMPs, MMP2 and MMP9 appear most important for tumor invasion due to their ability to degrade the ECM and basement membrane." (PMID 27556184, 2016). "MMP-2 and MMP-9, two of the main proteolytic enzymes for degrading the extracellular matrix (ECM) and the basement membrane, are known to be critical for tumor metastasis." (PMID 27329841, 2016). "In this process, MMPs are activated and, in particular, the expression of MMP-2 and MMP-9 is upregulated within the tumor microenvironment." (PMID 27876012, 2016).
tumor (continued). "MMP-2 is mostly secreted by fibroblast-like stromal cells surrounding BCC tumors, and rarely by keratinocytes and BCC tumor cells." (PMID 27271600, 2016). "Several downstream target genes of WNT/β-catenin signaling, such as CD44, C-myc, MMP2, MMP7 and TIMP2, can affect tumor growth, proliferation, invasion and metastasis." (PMID 27835587, 2016). "Among MMPs family, MMP2 and MMP9 have been confirmed playing important role in enhancement of tumor metastasis." (PMID 26701209, 2016). "We further demonstrated that PGC1α induced MMP2 and CD44 expression and overexpression of PGC1α restored aggressive phenotype of tumor cells suppressed by grifolin." (PMID 27626695, 2016). "In support of an anti-tumor role for MMPs, treatment with the MMP inhibitor tanomastat, which has selective activity against MMP2, MMP3 and MMP9, was shown to lead to a worse outcome compared to standard treatments." (PMID 26956475, 2016). "Immunoblot analysis of tumor tissue lysates showed that Malme3MR-miR-217 cells expressed lower level of CAGE, MDR1 and MMP-2 than Malme3MR cells." (PMID 26863629, 2016). "Since only a limited number of frozen tumor samples were available from BEVERLY-2 patients, we analyzed MMP2 and MMP9 mRNA expression in 137 clinical IBC samples profiled within the World IBC Consortium (E-MTAB-1006, E-MTAB-1547 and GSE22597)." (PMID 26921265, 2016). "MMP-2 and MMP-9 play important roles in the degradation of the extracellular matrix and basement membrane, promoting tumor invasion and metastasis." (PMID 27152521, 2016). "In particular, MMP-2 and MMP-9 are collagenases that are crucial for tumor invasion and metastasis through degradation of collagen IV." (PMID 25927362, 2015). "For example, by inhibiting the activity of MMP-2, TIMP-2 can block tumor cell invasion thereby acting an anti-tumorigenic factor." (PMID 26361584, 2015). "The immune-reactivity scores for the expression of mTOR and p-mTOR as well as for MMP2, MMP7, and MMP9 in the tumor center correlated each with its expression at the invasive front (p < 0.001)." (PMID 26652716, 2015). "Among them, MMP-2 and MMP-9 are the enzymes that are most crucial to tumor invasion due to their ability to degrade the extracellular matrix (ECM) and basement membrane." (PMID 26043036, 2015). "The invasiveness occurred through MMP2 and MMP3, while inhibition of VEGFA decreased the tumor growth." (PMID 26308848, 2015). "Subsequent binding to the RE-1 response element of the matrix metalloproteinase 2 (MMP2) gene enhancer element activates the transcription of MMP2, thereby promoting tumor metastasis." (PMID 25790262, 2015). "obASCs not only contribute to the primary tumor growth, but these cells also enhance metastasis through a leptin-mediated pathway(s) involving SERPINE1 and MMP-2." (PMID 26286584, 2015). "Because MMP2/9 play important roles in tumor invasion and metastasis, FAK contributes to the invasion and metastasis of HCC partly through regulating expression and activation of both MMP-2 and MMP-9." (PMID 26068982, 2015). "E-cadherin exhibited low expression, whereas vimentin, MMP-2, and MMP-9 exhibited high expression in tumor cells treated with doxycycline compared with the untreated group in both the membrane and cytoplasm." (PMID 26512779, 2015). "During bone resorption, bone matrix is degraded by enzymes, such as MMP-2 and MMP-9, and the room for neoplasms growth is obtained." (PMID 25879017, 2015). "Accordingly, we identified suppression of effector proteins related to tumor invasion, MMP2, MMP9, and E-cadherin, in miR-124-transfected tumor cells." (PMID 25969668, 2015). "Among this family of members, MMP-2 and MMP-9 have been characterized as crucial factors contributing to angiogenesis and tumor invasion." (PMID 25563361, 2015).
tumor (continued). "Immunohistochemistry revealed that the expression levels of CDX2 and matrix metalloproteinase-2 (MMP-2) were detected in each group, and the protein expression of CDX2 was increased in the tumor tissues from the nude mice in the pEGFP-C1-CDX2 group." (PMID 26005051, 2015). "It inhibits MMP-2, MMP-3, TIMP-1, and TIMP-3 in preventing tumor angiogenesis, and MMP-9 through an autocrine loop in blocking lung and liver metastasis mediated by stromal fibroblasts." (PMID 25909283, 2015). "Other proteins included adhesion receptors, such as ICAM-5 and selectin, tissue-remodeling factors, such as DKK-1 and MMP-2, and metabolic enzymes, such as adiponectin and insulysin, suggesting that EMMPRIN is a multifunctional regulator of tumor development." (PMID 26416452, 2015). "The attachment of these cells into their new sites is mediated in part by matrix-metalloproteinase-2 (MMP2); MMP2 is also responsible for invasion of the tumor deeper into the tissue." (PMID 26648788, 2015). "Matrix metalloproteinases (MMPs), including MMP-2 and MMP-9, facilitate the migratory or invasive potential of tumor cells by enzymatically degrading the extracellular matrix." (PMID 26155940, 2015). "In this study we found that the development and growth of the tumor by SaOS2 cells on CAM is favored by the elevated expression of VEGF165, MMP2 and MMP at mRNA level." (PMID 26109911, 2015). "Various pathological processes such as tumor invasion, atherosclerosis, inflammation, and rheumatoid arthritis can stimulate MMP-9 synthesis and secretion, whereas MMP-2 is usually constitutively overexpressed." (PMID 25670016, 2015). "Tumor cells degrade and remodel the extracellular matrix (ECM) by excessively secreting matrix metalloproteinases (MMPs) such as MMP-2 and MMP-9." (PMID 26170886, 2015). "ETV5 has also been shown to increase the transcription of matrix metalloproteinases 2 (MMP2) and HEP27, which allow for cellular invasion by degrading extracellular matrix and prevent apoptosis in tumor cells, respectively." (PMID 26356073, 2015). "MMP2 and MMP9 play vital roles in tumor metastasis and invasion via the degradation of various proteins of the extracellular matrix and destruction of histological barriers." (PMID 26649302, 2015). "All genes were significantly down-regulated in 2D culture relative to the parental tumor, with the most differentially expressed markers including CD105, NRP1, FGFR3 and MMP2 (p < 0.005)." (PMID 26203665, 2015). "Western blot analysis was conducted on tumor samples to validate the expression of SERPINE1 and MMP-2 proteins." (PMID 26286584, 2015). "Gelatinases such as MMP-2 and MMP-9 play a crucial role in tumor cell aggressiveness such as invasion and metastasis." (PMID 26608825, 2015). "Activated STAT3 leads to transcription of various target genes, such as cyclin D1, Bcl-2, Bcl-xL, matrix metalloproteinase 2 (MMP2), and VEGF, to regulate cell survival, angiogenesis, immune evasion, and inflammation in tumor microenvironment." (PMID 25789853, 2015). "The screening analysis by Proteome Profiler showed distinctly altered expression of sE-cadherin, E-selectin, MMP2, MMP9, TIMP1, TIMP2, Galectin and Clusterin in the serum of tumor patients compared to controls." (PMID 25967040, 2015). "As assessed by the immune-reactivity scores, only MMP2 was more markedly expressed at the invasive front, whereas MMP9 was homogenously expressed throughout the invasive front and the tumor center." (PMID 26652716, 2015). "Taken together, our results demonstrate that miR-29b serves as a tumor metastasis suppressor, which suppresses NSCLC cell metastasis by directly inhibiting MMP2 expression." (PMID 26063204, 2015). "Among all members of MMPs family, MMP-2 and MMP-9 are the most concerned and their functions have been well-characterized during tumor invasive process." (PMID 26177288, 2015).
tumor (continued). "COX-2 inhibitors suppress the expression and secretion of MMP-2 and-9, suggesting that COX-2 also promotes tumour angiogenesis and tumour invasion." (PMID 25403643, 2015). "Some transcription factors (such as SNAIL and SLUG) and matrix metalloproteinases (MMP2 and MMP9), were widely interpreted as the critical molecules in tumor invasion." (PMID 26575197, 2015). "The results of the present study confirmed that the overexpression of MMP-2 and MMP-9 is likely to increase tumor invasion and metastasis." (PMID 25667651, 2015). "From an upfront screen, we went on to demonstrate that genistein suppresses expression of matrix metalloproteinase 2 (MMP2) and of Fms-Related Tyrosine Kinase 4 (FLT4), and that it does so in cells in vitro and in tumor tissue in vivo." (PMID 25605009, 2015). "Simultaneously, the MMP-2 and MMP-9 protein expression of the tumor xenograft were downregulated in mice injected with SiCHD1L/MDA231 cells." (PMID 26599012, 2015). "Our study expected that after the GNP core were degraded by MMP-2, the released small-sized Angio-DOX-DGL-PEG penetrated into the regions away from the tumor blood vessels to kill more cancer cells." (PMID 26517810, 2015). "Silencing TRB3 not only decreased the basal level of critical tumour-promoting factors such as EGFR, COX2, MMP1, MMP-2, MT-MMP, Snail, Twist and c-Myc but also protected them from the IGF-1 induction." (PMID 26268733, 2015). "In the present study, our results revealed that scutellarein not only decreased the expression of MMP-2, -9 and -14, but also induced apoptosis by suppressing the proliferation of HT1080 cells, thereby attenuating tumor development and metastasis." (PMID 25394920, 2015). "The expression levels of AR, MMP-2 and MMP-9 in HCC tissues and tissues adjacent to the tumor were measured by immunohistochemical staining assay." (PMID 25667651, 2015). "RECK suppresses tumor invasion by negatively regulating at least three members of the matrix metalloproteinase family: MMP-9, MMP-2, and MT1-MMP." (PMID 26431549, 2015). "Given that MMPs and EMT were involved in tumor cells metastasis, we further investigated the link between HDAC4 expression and E-cadherin, Vimentin, MMP2 and MMP9 expression." (PMID 26441331, 2015). "In contrast, blocking RhoA activity significantly inhibits MMP2 and MMP9 expression, tumor invasion, and lung metastasis." (PMID 25889562, 2015). "Since MMP9 and MMP2 regulate tumor microenvironment and tumor metastasis, in theory, the invasion and metastasis of tumor can be inhibited through decreasing the activity of MMP9 and MMP2." (PMID 26674531, 2015). "The production of MMP-2 and MMP-9 are considered by many publications as tumor markers, in which, they promote the development and progression of tumor cells, along with facilitating migration, invasion and metastasis." (PMID 26588686, 2015). "Specifically, activated STAT3 increases the invasive abilities of BrC cells by initiating the transcription of the MMP2 and MMP9 genes, whereas blocking STAT3 activity suppresses MMP2 and MMP9 expression, tumor invasion, and lung metastasis." (PMID 26360780, 2015). "Matrix metalloproteinase 2 (MMP-2), a main member of MMPs, is thought to be the key enzyme for metastasis of tumor with the physiological action of degrading type IV collagen." (PMID 25816052, 2015). "Downregulation of JWA was found to be crucial for the invasion and metastasis of human tumor through elevated FAK expression, the induction of RhoA and MMP-2 activation." (PMID 25925371, 2015). "AR, MMP-2 and MMP-9 expression levels in HCC tissues have the potential to be employed as predictors of the progression of local cancer invasion and the tumor stage." (PMID 25667651, 2015).
tumor (continued). "It was also noticed that the development of tumor growth by SaOS2 cells on CAM is majorly depends on the activation of VEGF165, MMP2 and MMP9 and is in concordance with other animal model studies." (PMID 26109911, 2015). "The number of lung metastatic tumor nodules in each group was strongly reduced by treatment with Dasatinib, AZD6244, ABT-199, and MMP2 inhibitor I." (PMID 25826088, 2015). "Tumor angiogenesis is enforced by autocrine regulation of HMGB-1 in EC through increased expression of key pro-angiogenic genes as PDGF-A, FGF and MMP-2, that we found to be strongly up-regulated in tumors from hCD31 mAb treated mice." (PMID 25362644, 2014). "MMP-2 promotes cleavage of ECM proteins and is intensively expressed by tumour and stromal components of cancer, while MMP-9 modulates permeability of vascular endothelium." (PMID 24912879, 2014). "MMP-2 degrades components of the extracellular matrix (ECM) proteins, contributing to tumour invasion and metastasis." (PMID 25491408, 2014). "We found that most of matrix metalloproteinases (MMPs), especially MMP2 and MMP9, is down-regulated in cancer tissues compared to non-tumor tissue." (PMID 24622401, 2014). "Consequently, the increase release of the biotin-fragment from the avidin-modified MMP2 peptide used in the present study after its cleavage in the tumor could potentially represent an attractive target for avidin-conjugated nanoparticles containing a therapeutic agent." (PMID 24919932, 2014). "MMP-2, MMP-9 and uPA act as pivotal roles in degrading ECM and are involved in tumor metastasis and invasion." (PMID 25222667, 2014). "In particular, MMP-2 is upregulated in SACC and a number of other malignant tumors, and contributes to the invasion of tumor cells by degrading the ECM." (PMID 24765174, 2014). "As MMP-2 and MMP-9 have a critical function in tumor cell invasion, the inhibitory effect of icotinib on the expression of MMP-2 and MMP-9 was investigated." (PMID 25120710, 2014). "We identified multiple genes that were induced or repressed upon P4HA1 knockdown including those involved in tumor growth and invasion such as MMP1, MMP2 and FLRT3, among others." (PMID 25115393, 2014). "Among matrix metalloproteases (MMPs), a family of zinc dependent endopeptidases, MMP-2 and MMP-9 have been considered to be critical for tumor growth, invasion and metastasis." (PMID 24885308, 2014). "The interaction of HMGB1 with RAGE leads to activation of the NF-κB, MAPK, and type IV collagenase (MMP-2/MMP-9) signaling pathways, all of which degrade extracellular matrix protein and play a major role in tumor invasion and metastasis." (PMID 25356587, 2014). "We found that while expression of MMP-2 and MMP-9 was reduced in Spn4A-expressing tumor cells, mRNA expression levels of TIMP-1 and TIMP-2 was significantly increased." (PMID 24961901, 2014). "The serum level of MMP2 and MMP9 were both up-regulated under MT treatment under the mechanical damage indicated the highly migration ability of tumor cells while MMP13 also showed the enhanced trend." (PMID 24804772, 2014). "Among MMPs, MMP-2 and MMP-9 are regarded as the critical indicators for tumor cell invasion and metastasis." (PMID 24797571, 2014). "In our previous study, the serum levels of MMP-2 and TIMP-2 were significantly lower in CRC patients than in healthy subjects and decreased with tumor stage." (PMID 24395652, 2014). "Most showed strong expression of mRNAs and proteins of both MT1-MMP and MMP-2 in both HCC cells and stromal cells in the invading border of tumor nests." (PMID 24978432, 2014). "EMMPRIN proteins have been well documented to stimulate the synthesis of MMPs such as MMP-1, MMP-2, MMP-3, and MMP-9 in fibroblast and tumor cells." (PMID 24705283, 2014). "Among the studied genes, the overexpression of the following metalloproteinases in the tumor tissue can be correlated to at least one clinicopathological variable: MMP-1, MMP-2, MMP-9, MMP-11, and MMP-16." (PMID 24737953, 2014).